MYOF (myoferlin)
Diseases named in the same sentence as MYOF in open-access papers (continued):
Sharing a sentence is not in itself a finding about the gene and the disease.
tumor (continued). "Subsequently, we further investigated potential CAF-specific functions of myoferlin that contribute to tumor aggressiveness." (PMID 41062852, 2025). "By combining PAAD whole-tumor and single-cell transcriptomic analyses with immunohistochemistry and 2D/3D in vitro models, we link stromal myoferlin to tumor aggressiveness." (PMID 41062852, 2025). "Accordingly, the genetic depletion of myoferlin in the tumor stroma and the pharmacological targeting of myoferlin alike reduced tumor desmoplasia in orthotopic KPC mice." (PMID 41062852, 2025). "We subcutaneously implanted MC38 shMYOF cells into C57BL/6 mice and found that both MYOF knockdown and apatinib gavage treatment significantly inhibited tumor growth, leading to tumor shrinkage." (PMID 39941891, 2025). "To further elucidate the impact of MYOF knockdown on the tumor microenvironment, we analyzed tumor-infiltrating lymphocytes (TILs) in MYOF-KD tumors in mice." (PMID 39941891, 2025). "Next, to investigate tumor cellularity as potential bias during GSEA analysis, we assessed tumor cellularity according to MYOF expression since tumor samples are heterogeneous and constituted by multiple different cell types." (PMID 41062852, 2025). "A further investigation of myoferlin in the context of tumor-restraining ECM components, such as collagen XV and biglycan is necessary to validate a specific tumor-promoting ECM function of myoferlin." (PMID 41062852, 2025). "Owing to the suggested implication of myoferlin in tumor desmoplasia, we aimed to assess the impact of MYOFKD myCAFs on PAAD tumor biology in vivo." (PMID 41062852, 2025). "Targeting MYOF alongside ICB therapy or using apatinib as an adjuvant treatment can enhance anti-tumor efficacy." (PMID 39941891, 2025). "As stromal MyofKO impaired tumor desmoplasia in mice, we aimed to assess the effect of myoferlin targeting in a pharmacological model, thus enabling an initial tumor establishment prior to treatment administration." (PMID 41062852, 2025). "A series of mouse models were established to assess the effects of apatinib and MYOF knockdown on tumor progression, immune cell infiltration, and immune checkpoint protein response." (PMID 39941891, 2025). "Several pro-oncogenic properties of myoferlin in PAAD tumor cells have been described previously, including the implication of myoferlin in lysosome integrity and metabolic flexibility." (PMID 41062852, 2025). "Immunohistochemistry also revealed significantly reduced PD-L1 expression in tumor tissues of the apatinib-treated, MYOF knockdown, and combination groups compared to controls." (PMID 39941891, 2025). "The results show that MYOF is expressed not only in malignant tumor cells but also widely across most types of immune cells." (PMID 39941891, 2025). "We compared the levels of TGF-β in tumor tissue and found that the levels were lower in the apatinib, MYOF knockdown, and combination groups compared to the control group." (PMID 39941891, 2025). "Since mitochondria are involved in PDAC relapse and tumor growth, we aimed to understand the mechanism linking myoferlin silencing to mitochondrial dynamics." (PMID 38368370, 2024). "Previous studies have shown that MYOF is expressed at high levels in tumour cells and prevents lysosomal damage in tumour cells, thereby prolonging their lifespan." (PMID 35984564, 2022). "We verified that the most upregulated membrane protein myoferlin (MYOF) was metastasis-related protein whose knockdown suppressed the malignant phenotype of NPC tumor cells." (PMID 34178975, 2021). "The expression levels of MYOF, Rab7, and Rab32 in tumor tissues were significantly higher than those in normal tissues, implying the co‐expression relationships between MYOF and Rab7, and between MYOF and Rab32." (PMID 33634965, 2021). "Emerging evidence suggested that MYOF promotes tumor progression by enhancing the stability of RTKs." (PMID 33634965, 2021).
tumor (continued). "More specifically, myoferlin depletion in TNBC tumor cells damages vesicle trafficking, leading to a misbalance between unsaturated and saturated fatty acids." (PMID 32296646, 2020). "In this review, we will present a summary of the functions and roles of myoferlin in normal and tumour cells with updated knowledge." (PMID 31475450, 2019). "Here under, this review discusses that ferlins, mainly myoferlin, are involved in neoplastic diseases and are potential therapeutic targets." (PMID 31443490, 2019). "MYOF depletion results in high levels of E-cadherin and low levels of fibronectin and vimentin, indicating that MYOF precipitates EMT to promote tumor invasion." (PMID 31828126, 2019). "Accordingly, myoferlin-silenced HCT116 cell produced significantly smaller tumours in a chorioallantoic in ovo model." (PMID 30850580, 2019). "With respect to the proportion of tumor cells expressing these markers, 40 (13.2%) samples were scored as having low and 264 (86.9%) were scored as having high MYOF expression." (PMID 31477752, 2019). "In mice bearing solid LLC lung tumours, the intratumoral injection of myoferlin siRNA mixed with a lipidic vector reduced the tumour volume by 73%." (PMID 31443490, 2019). "MYOF depletion increases focal adhesion maturity and cell-substrate adhesion, which renders tumor cells a more epithelial-like morphology." (PMID 31828126, 2019). "Using TCGA-COAD data, we evaluated myoferlin gene expression according to prognostic stage and Tumour, Node, Metastasis (TNM) categories." (PMID 30850580, 2019). "In melanoma, MYOF contributes to the formation of Vasculogenic mimicry (VM), an important mechanism to facilitate tumor metastasis." (PMID 31828126, 2019). "WJ460 treatment led to decreased invasion through Matrigel in all four cell lines derived from other tumor types with high MYOF." (PMID 30213946, 2018). "The decrease in MMP‐2 induced by MYOF depletion then affects cell migration and severely suppresses cell invasion, which are required for VM formation by tumour cells." (PMID 29164766, 2018). "Collectively, these observations suggest that WJ460 attenuates the metastatic ability of other tumor types that express a high level of MYOF." (PMID 30213946, 2018). "We found out that myoferlin expression is negatively correlated with tumor size and glycolytic activity evaluated by 18F-DG-PET, and overall patient survival." (PMID 29720728, 2018). "For the first time, we show that myoferlin expression, particularly nuclear myoferlin expression, is highly predictive of poor overall survival, tumor recurrence, perineural invasion, higher T stage and distal metastasis in OPSCC patients." (PMID 26919244, 2016). "Although the consequences for tumor progression are evident, additional studies need to be conducted in order to understand how myoferlin contributes to the exosome uptake in the target cells." (PMID 27845903, 2016). "Immunohistochemical staining with anti-human MYOF demonstrated that MYOF-positive tumor cells in control mice were found in the surrounding adipose and connective tissues to create tumors with jagged edges." (PMID 24586247, 2014). "However, the use of cytotoxic agents in combination with myoferlin targeting is likely mandatory for efficient tumor regression." (PMID 41062852, 2025). "Notably, fibroid tumor disease ranked as the top enriched disease in both MyoF vs. MyoN and MyoT vs. MyoN comparisons." (PMID 40474053, 2025). "Further research is indeed necessary to assess whether tumor cell and stromal myoferlin collectively contribute to PAAD tumor aggressiveness." (PMID 41062852, 2025). "Patients with a predominant MYOFlow stroma showed nearly doubled median overall survival (31.86 months) compared to patients with MYOFhigh stroma (16.09 months), supporting the implication of myoferlin in tumor fibrosis and potential tumor-promoting functions of the MYOFhigh TME." (PMID 41062852, 2025).
tumor (continued). "Furthermore, Disease Gene Network analysis highlighted fibroid tumor disease as the top enriched condition in both MyoF vs. MyoN and MyoT vs. MyoN comparisons, reinforcing the functional relevance of these transcriptomic changes to fibroid biology." (PMID 40474053, 2025). "However, the inevitable targeting of myoferlin in tumor restraining CAFs, such as CD105neg CAFs, remains a challenge and deserves to be addressed in the future." (PMID 41062852, 2025). "This suggests that apatinib and MYOF knockdown may inhibit tumor progression through the same pathway." (PMID 39941891, 2025). "The production of myoferlin-silenced tumor cells has provided another element that may help explain the role of ferlin: these tumors lacked functional blood vessels, an effect that may be due to a reduction in VEGFA exocytosis." (PMID 37538852, 2023). "Previous work reported that MYOF promotes tumor growth by modulating VEGF‐induced angiogenesis." (PMID 33634965, 2021). "Myoferlin is a multifunctional protein that was involved in the invasion of tumour cells." (PMID 34013402, 2021). "To extend our findings to tumor tissues, we investigated whether the protein level of MYOF was correlated with metastasis in surgically resected human NPC specimens." (PMID 34178975, 2021). "This evidence indicated that myoferlin was involved in the proliferation, invasion and migration of tumour cells, the mechanism of which mainly included promoting angiogenesis, vasculogenic mimicry, energy metabolism reprogramming, epithelial‐mesenchymal transition and modulating exosomes." (PMID 31475450, 2019). "Myoferlin knockdown significantly decreases tumour growth and metastasis of HNSCC." (PMID 31475450, 2019). "Results in the present work may reflect the role of MYOF in tumor metastasis and this raises the possibility to assess the clinical association of MYOF and metastasis." (PMID 30213946, 2018). "We next investigated whether WJ460 exhibits anti-metastatic potential in other tumor types with high MYOF expression." (PMID 30213946, 2018). "In PDAC, myoferlin has a tumor-promoting function by increasing cell proliferation." (PMID 29720728, 2018). "Indeed, although the presence of exosomal myoferlin has been reported in several proteomic analyses of tumor-derived exosomes, to our knowledge, the definitive proof of its presence in exosomes has not been provided as yet." (PMID 27845903, 2016). "However, our study brings forward an additional important role for myoferlin in tumor progression, namely its ability to exert functional impact on exosome biology." (PMID 27845903, 2016). "Myoferlin expression was predominately cytoplasmic in the OPSCC tumor samples." (PMID 26919244, 2016). "Furthermore, these tumors contained MYOF immunoreactivity within the surrounding connective tissue, further indicating local invasive activity of implanted human tumor cells." (PMID 24586247, 2014). "Finally, our in vitro results suggested that silencing MYOF can significantly alter the biomechanics of tumor growth and morphogenesis." (PMID 24586247, 2014). "Finally, we demonstrated that MYOF depletion also significantly affects tumor growth and progression in vivo." (PMID 24586247, 2014). "Finally, we used TFM to investigate how depletion of MYOF alters the traction stress generated by MDA-MB-231 tumor cells." (PMID 24586247, 2014). "To address whether MYOF loss could result in altered in vivo tumor formation, we transplanted MDA-231MYOKD cells into nude mice to examine the role that MYOF may play in tumor growth and early invasion." (PMID 24586247, 2014). "Of note, while depleting stromal myoferlin and impairing tumor desmoplasia alone could result in more aggressive tumors due to improved vascularization and promoted tumor cell dissemination, we did not observe increased tumor burden upon stromal myoferlin depletion." (PMID 41062852, 2025).
tumor (continued). "Even though this is likely an overestimation, the fact that more than 40% of these genes are differentially expressed between MyoF and fibroid tumor tissue indicates that a substantial number of these genes could be the direct target of risk loci and contribute to the disease pathology." (PMID 38326302, 2024). "In addition, myoferlin knockdown significantly reduced IL-6-mediated tumor growth and metastasis." (PMID 37538852, 2023). "However, in specific tumours, myoferlin is overexpressed and plays critical roles." (PMID 31475450, 2019). "In conclusion, our data suggest that apatinib treatment or MYOF knockdown represents a promising therapeutic approach for CRC, potentially enhancing anti-tumor immunity." (PMID 39941891, 2025). "Integrative analysis showed that apatinib modulates MYOF expression via VEGFR2, resulting in decreased PD-L1 expression, increased CD8+ T cell infiltration, and reduced pro-tumor M2 macrophages." (PMID 39941891, 2025). "Our animal experiment results also proved that knockdown of MYOF or apatinib treatment increased the infiltration of CD8+ T cells, M1 macrophages, and activated DC cells, promoting anti-tumor immunity." (PMID 39941891, 2025). "Owing to the correlation between MYOF expression and tumor fibrosis in PAAD tumors, we used human PAAD scRNAseq data to assess the expression of MYOF across stromal cells, including CAFs, immune- and endothelial cells." (PMID 41062852, 2025). "Notably, we found that MYOF might have a potential novel immune regulatory role in tumor immunity." (PMID 34957301, 2021). "Clinical statistics also reveal that TNBC patients harboring overexpressed-myoferlin tumors experience worse distant metastasis-free and overall survivals, implying the clinical significance of myoferlin in TNBC tumor metastasis." (PMID 32296646, 2020). "MYOF depletion decreases the oxidative phosphorylation (OXPHOS) as well as ATP production and redirects tumor cells toward glycolysis." (PMID 31828126, 2019). "Myoferlin, a ferlin family member protein overexpressed in PDAC, is involved in plasma membrane biology and has a tumor-promoting function." (PMID 29720728, 2018). "We used selected PDAC tumor samples and PDAC cell lines together with small interfering RNA technology to study the role of myoferlin in energetic metabolism." (PMID 29720728, 2018). "Total lesion glycolysis (TLG40) and standardized uptake value (SUVmean, SUVmax) were negatively correlated with the myoferlin maximal score of the tumor, indicating that the more a PDAC is glycolytic, the less it has myoferlin." (PMID 29720728, 2018). "The results from these combined investigations point to a critical role for MYOF in membrane receptor signaling and MMP production and secretion, potentially contributing to tumor cell chemotaxis and invasion." (PMID 24586247, 2014). "Therefore, the effect of MYOF depletion on cell migration observed in vitro, including reduced cell detachment and a switch to collective epithelial-like cell migration, correlate with our in vivo observations of decreased invasive processes and a more regular/circular tumor morphology." (PMID 24586247, 2014). "This indicates that apatinib treatment or MYOF knockdown primarily influences the changes in immune cell infiltration within the tumor rather than in the spleen." (PMID 39941891, 2025). "Finally, we assessed the anti-desmoplastic potential of a stromal MyofKO and the myoferlin-targeting small molecule WJ460 in an orthotopic KPC mouse model and showed indeed reduced tumor desmoplasia." (PMID 41062852, 2025). "Additionally, we provide evidence that apatinib exerts additional anti-tumor effects by inhibiting the activation of VEGFR2, thereby affecting the expression of MYOF." (PMID 39941891, 2025). "In agreement with the immunofluorescence results, MYOF protein was found to be upregulated in tumor tissue, mainly within the cytoplasm, whereas little or no MYOF protein was detected in gastric glandular cells." (PMID 36147922, 2022).
tumor (continued). "In vivo, mice bearing LCC solid tumor exhibit significant reduction in tumor body in the absence of MYOF." (PMID 31828126, 2019). "In detail, depletion of myoferlin in tumour cells from SRF‐VP16‐derived murine HCCs induced a senescence phenotype, which suggested that myoferlin might be a novel therapeutic target." (PMID 31475450, 2019). "Myoferlin was reported as expressed in human non-small cell lung cancer tissues where it was correlated with VEGFR2, thyroid transcription factor (TTF)-1 and transformation-related protein (p63), especially in the low stage tumours." (PMID 31443490, 2019). "This highly refined list of selection candidates, which contains genes related to muscle metabolism and angiogenesis (MYOF, MAP2K5) and tumor suppression (MCC), yields valuable insight for future examination of adaptation in both Mongolian and Tibetan ethnic groups." (PMID 23874230, 2013). "We observed no change in the growth rates of the three cell types, indicating that MYOF does not profoundly alter tumor cell growth." (PMID 22761893, 2012). "Therefore, we investigated myoferlin expression in a murine PAAD scRNAseq dataset that not only recapitulates distinct CAF subtypes (iCAF/myCAF), but also assesses CAF lineages during tumor progression (Fig. EV2D–F)." (PMID 41062852, 2025). "Although the correlation between MYOF expression and tumor purity was not very significant (R = 0.129, P = 9.27e − 02), MYOF was correlated with some dominant immune cell infiltration levels, such as B cells, CD8+ T cells, macrophages, neutrophils, and dendritic cells." (PMID 34957301, 2021). "The decrease of RAB7A expression observed in absence of myoferlin could therefore reflect another mechanism that could explain the observed anti-tumor effect." (PMID 27845903, 2016). "For instance, myoferlin, a membrane protein of ferlin family, has been reported to be involved in tumor progression by promoting angiogenesis, energy metabolism reprogramming, EMT and exosome modulation, which may be a potential target for tumor detection and therapy." (PMID 39466826, 2024).
infection (5 papers, 2021 to 2026). The state of being infected such as from the introduction of a foreign agent such as serum, vaccine, antigenic substance or organism. "Here we discover and confirm myoferlin's association with IAV vRNPs in the cytoplasm and colocalisation with Rab11 during late stages of infection." (PMID 41654495, 2026). "In the current study, we provide evidence that HBZ induces expression of MyoF, which also contributes to infection." (PMID 36827461, 2023). "In HTLV-1-infected T-cells, specific inhibition of MyoF using the drug, WJ460, or shRNA-mediated knockdown of MyoF reduced infection efficiency." (PMID 36827461, 2023). "Three proteins, Dynein light chain-1, Dynein light chain-2 and Myoferlin were detected in all infection periods." (PMID 34733798, 2021). "HBZ was previously shown to enhance HTLV-1 infection by activating the expression of ICAM1 and MYOF, and in this study, we found that HBZ upregulates two additional cellular genes involved in infection: COL4A1 and GEM." (PMID 37375521, 2023).
cardiovascular disease (1 paper, 2022). "The expression of PDLIM5 in the ‘cardiovascular disease’ protein category and MYOF in the ‘skeletal and muscular disorders’ protein category were down-regulated in ADSCs cultured in all SFM than in FBS containing media." (PMID 35597800, 2022).
genetic disease (1 paper, 2019). "The clinical phenotype in combination with in vitro and in vivo studies allowed us to classify the detected MYOF variant as likely pathogenic and to link for the first time MYOF with a human genetic disease." (PMID 31297131, 2019).
kidney disease (1 paper, 2022). "Although PLPPR1 and SFXN1 genes have not been reported to be associated with kidney disease, the current study found that PLPPR1 and SFXN1 were significantly positively correlated with QDPR and negatively correlated with HAS2 and MYOF." (PMID 35320116, 2022).